CERNA1 (competing endogenous lncRNA 1 for miR-4707-5p and miR-4767)
Synonyms: LOC100129973
Gene: Long non-coding RNA gene on chromosome 15 (52,179,997 to 52,230,123, forward strand). Ensembl gene ENSG00000259577.
Diseases named in the same sentence as CERNA1 in open-access papers:
CERNA1 is named in the same sentence as 2 diseases in open-access papers, as found by Europe PMC text mining. Sharing a sentence is not in itself a finding about the gene and the disease.
CERNA1 shares sentences with these, for which no sentence is quoted: atherosclerosis (1 paper); ovarian carcinoma (1).